TRDV1 (T cell receptor delta variable 1)
Description:
V region of the variable domain of T cell receptor (TR) delta chain that participates in the antigen recognition. Gamma-delta TRs recognize a variety of self and foreign non-peptide antigens frequently expressed at the epithelial boundaries between the host and external environment, including endogenous lipids presented by MH-like protein CD1D and phosphoantigens presented by butyrophilin-like molecule BTN3A1. Upon antigen recognition induces rapid, innate-like immune responses involved in pathogen clearance and tissue repair. Binding of gamma-delta TR complex to antigen triggers phosphorylation of immunoreceptor tyrosine-based activation motifs (ITAMs) in the CD3 chains by the LCK and FYN kinases, allowing the recruitment, phosphorylation, and activation of ZAP70 that facilitates phosphorylation of the scaffolding proteins LCP2 and LAT. This lead to the formation of a supramolecular signalosome that recruits the phospholipase PLCG1, resulting in calcium mobilization and ERK activation, ultimately leading to T cell expansion and differentiation into effector cells. Gamma-delta TRs are produced through somatic rearrangement of a limited repertoire of variable (V), diversity (D), and joining (J) genes. The potential diversity of gamma-delta TRs is conferred by the unique ability to rearrange (D) genes in tandem and to utilize all three reading frames. The combinatorial diversity is considerably increased by the sequence exonuclease trimming and random nucleotide (N) region additions which occur during the V-(D)-J rearrangements.
Synonyms: hDV101S1
Gene: T-cell receptor variable (V) gene on chromosome 14 (22,096,032 to 22,096,619, forward strand). Ensembl gene ENSG00000211804.
Subcellular location: Cell membrane
Gene Ontology:
Biological process: immune response
Cellular component: immunoglobulin complex; plasma membrane
Homologues: Orthologues: mouse Trav15-2-dv6-2 (58% identical), mouse Trav15d-2-dv6d-2 (58% identical), mouse Trav15n-2 (58% identical), mouse Trav15d-1-dv6d-1 (56% identical), mouse Trav15n-1 (56% identical), mouse Trav15-1-dv6-1 (54% identical), rat AABR07017768.6 (53% identical), rat AABR07017770.2 (53% identical). Paralogues in human: TRAV14DV4 (56% identical), TRAV19 (56% identical), IGLV4-69 (30% identical), IGLV5-45 (30% identical), IGLV5-52 (30% identical), IGLV11-55 (29% identical), IGLV2-11 (29% identical), IGLV2-18 (29% identical), IGLV4-60 (29% identical), IGLV5-37 (29% identical), TRAV18 (29% identical), TRDV3 (29% identical), and 81 more.
Diseases named in the same sentence as TRDV1 in open-access papers:
TRDV1 is named in the same sentence as 5 diseases in open-access papers, as found by Europe PMC text mining. Sharing a sentence is not in itself a finding about the gene and the disease. The quoted sentences say what the papers report.
melanoma (2 papers, 2024 to 2026). A malignant, usually aggressive tumor composed of atypical, neoplastic melanocytes. "Here we demonstrate that intratumoral TRDV1 transcripts (encoding the TCRδ chain of Vδ1+ γδ T cells) predict anti-PD-1 CPI response in patients with melanoma, particularly those harboring below average neoantigens." (PMID 38172341, 2024). "Furthermore, reanalysis of RNA sequencing data from the INSPIRE trial, evaluating the effect of pembrolizumab treatment across a variety of advanced solid cancers including melanoma, showed that higher than median TRDV1 expression in tumor biopsies was linked to prolonged OS." (PMID 41558811, 2026). "In patients with melanoma under anti-PD-1 therapy, we observed a decrease in the percentage of CD57+ Vδ1 T cells, an increase in TRDV1 repertoire diversity, but no skewing of the CDR3 spectratype, suggesting polyclonal expansions of less-abundant CD57− Vδ1 clones." (PMID 41558811, 2026).
breast carcinoma (1 paper, 2022). "We applied CCK-8, Edu, Colony formation and Wound healing assays to detect the functions of ULBP2 and TRDV1 in breast cancer cells." (PMID 36092942, 2022). "We assessed the impact of ULBP2 and TRDV1 knockdown on breast cancer cell functions." (PMID 36092942, 2022). "In addition, a further research was made on the functions of high risk immune gene ULBP2 and low risk immune gene TRDV1 which regulated by RUNX3, the results showed that down-regulation of ULBP2 suppressed breast cancer cell proliferation and TRDV1 had the opposite functions." (PMID 36092942, 2022). "Finally, the dual luciferase reporter assay was used to verify the regulation of RUNX3 on potential target genes ULBP2 and TRDV1, and the effects of ULBP2 and TRDV1 on the growth of breast cancer cells were explored by CCK-8, colony formation and wound healing assays." (PMID 36092942, 2022). "Then, both univariate and multivariate logistic regression analyses demonstrated that 6 genes regulated by the RUNX family had a significant relationship with the prognosis of breast cancer patients, including PSME2, ULBP2, IL18, TSLP, NPR3, and TRDV1." (PMID 36092942, 2022).
tumor (7 papers, 2022 to 2026). "In contrast to peripheral blood, high TRDV1 expression in the tumor was significantly associated with favorable OS in stage IIIc and IV patients." (PMID 41558811, 2026). "Although rare, B2M alterations were also significantly associated with increased expression of TRDV1/TRDV3 loci in this context (two-sided linear regression, P = 2.2 × 10−17, adjusted for tumour type)." (PMID 36631610, 2023). "Using TRDV1 expression in pre-treatment tumor biopsies as a proxy for intratumoral Vδ1 T cells, we found that patients with above-median expression of TRDV1 had significantly increased survival compared with those with below-median expression." (PMID 35637401, 2022). "Moreover, B2MMUT tumours showed overexpression of multiple KIRs, which clustered together with TRDV1 and TRDV3 on the basis of hierarchical clustering." (PMID 36631610, 2023). "First, using 5’RACE on a mixed lymphocyte-tumor cell culture (MLTC), we identified TRDV1 5’-untranslated region (UTR) and complete coding sequence rearranged productively to TRAJ24." (PMID 38077312, 2023). "Despite the low patient numbers and high heterogeneity regarding tumour types and biopsy locations of this cohort, we confirmed increased TRDV1 and TRDV3 expression in B2MMUT tumours pan-cancer (two-sided linear regression, P = 0.017, adjusted for tumour type and biopsy site)." (PMID 36631610, 2023). "However, only the expression level of TRGV9, but not TRDV1, was correlated with TCF7, a stem‐like T cell marker in tumor tissues." (PMID 40091603, 2025).
TRDV1 also shares sentences with these, for which no sentence is quoted: cancer (2 papers); COVID-19 (1).